CCN2 (cellular communication network factor 2)
Diseases named in the same sentence as CCN2 in open-access papers (continued):
Sharing a sentence is not in itself a finding about the gene and the disease.
diabetes (continued). "Because CCN2/CTGF plays a major role in maintaining the ECM and wound healing, a greater emphasis has been placed on its involvement in diabetes-induced ECM remodeling." (PMID 32429045, 2020). "In CCN2/CTGF+/− mice, reduced CCN2/CTGF protein levels prevented BL thickening of retinal capillaries in streptozotocin (STZ)-induced diabetes." (PMID 32429045, 2020). "The connective tissue growth factor (CTGF or CCN2) is a profibrotic factor, a potential biomarker of renal damage in diabetes, and a potential therapeutic target, as demonstrated in experimental models of renal injury." (PMID 30647531, 2018). "In the present study, we observed that finerenone normalized upregulation of Ccn2 (also called connective tissue growth factor, CTGF) in DMHFD kidneys, which itself has a well established role in the pathogenesis of kidney disease in diabetes and in kidney function decline." (PMID 39582036, 2024). "By week 12 of diabetes, we identified a 2- to 3-fold increase in the kidney gene expression of Tgfb1, but found no increase in Ctgf/Ccn2 or Pdgfb mRNA levels." (PMID 38391050, 2024). "Connective tissue growth factor (CTGF/CCN2), a pro-inflammatory and profibrotic factor, has been shown to markedly elevated in fibrotic conditions, and strongly suggested to be involved in the development and progression of kidney injury in diabetes." (PMID 33445676, 2021). "CCN2/CTGF+/− mice showed no BL thickening, reduced pericyte loss, and formation of acellular capillaries 8 months after diabetes induction despite good glycemic control, suggesting a regulatory role of CCN2/CTGF in ECM remodeling at the early stages of diabetes." (PMID 32429045, 2020).
fibrosis (88 papers, 2009 to 2025). the formation of excess fibrous connective tissue in an organ or tissue in a reparative or reactive process. "Fibrosis contributes to the loss of intestinal compliance and impaired intestinal function and we showed that it was associated with heavy deposition of Connective Tissue Growth Factor (CTGF/CCN2)." (PMID 23259677, 2012). "Hepatic CCN2 expression was significantly induced in NASH patients with F3–F4 fibrosis and was positively correlated with hepatic Col1A1, Col1A2, Col3A1, or αSMA expression." (PMID 37629004, 2023). "Hepatic CCN2 expression was significantly induced in NAFLD patients with F3–F4 fibrosis compared to those with F0–F1 fibrosis." (PMID 37629004, 2023). "Fibrosis is also induced by bleomycin in lung, in which collagen overproduction is conducted by CCN2." (PMID 35682564, 2022). "CTGF/CCN2 plays a crucial role in tissue fibrosis, as it affects angiogenesis, migration, proliferation, and cell adhesion." (PMID 33801336, 2021). "Another mouse fibrosis model has shown that either CCN2 mRNA or an application of exogenous CCN2 protein seems required for the development of persistent fibrosis." (PMID 33428075, 2021). "In a 5-week CCl4 fibrosis model in mice, interstitial collagen deposition and mRNA and/or protein for collagen 1a1, αSMA or CCN2 were suppressed following administration of EVNorm over the last 2 weeks." (PMID 31998720, 2019). "The central role of CCN2 in fibroblast proliferation suggests that it could be a valuable target for treating fibrosis‐related disorders or promoting wound healing." (PMID 39898007, 2025). "In the present study, we showed that CCN2, which is reported as a promoter of fibrosis, is translocated into the nucleus in fibroblasts and binds to the regulatory region that is conserved among various species, which is located approximately −14 kb upstream from the initiation codon of Spi1." (PMID 41019779, 2025). "Some authors, described CCN2 as an autocrine regulator of cardiac fibrosis, demonstrating that cardiomyocyte-derived CCN2 is dispensable for cardiac fibrosis, but inhibiting CCN2 induction in activated fibroblasts abrogates the cardiac fibrotic response after angiotensin II infusion." (PMID 39273564, 2024). "When used as a preventive treatment in our overuse injury model in weeks 2 and 3 of a 3-week HRHF task, systemic provision of the anti-CCN2 blocked the development of muscle and neural fibrosis in parallel with significant reductions in collagen in each tissue." (PMID 37762168, 2023). "Moreover, specific inhibition of complement with compstatin (a C3 inhibitor) downregulated mRNA and protein expressions of CCN2/CTGF in lung tissue of sepsis-induced fibrosis model." (PMID 36276919, 2022). "Connective Tissue Growth Factor (CTGF), also known as CCN2, is another pleotropic growth factor that has emerged as an important mediator of normal and pathological tissue fibrotic responses and has been suggested to play a crucial role in SSc tissue fibrosis." (PMID 24175099, 2013). "The observed reduction in cardiac fibrosis and oxidative stress markers in CCN2-KO mice following DOX treatment underscores the functional implications of CCN2 in promoting DOX-induced cardiac damage." (PMID 39273564, 2024). "Pre-clinical and clinical data have highlighted the benefit of targeting the TGF beta pathway to reduce the cardiac fibrosis and the key role of the TGF beta-CCN2/CTGF axis." (PMID 35041643, 2022). "Fibrosis is triggered by the action of growth factors such as TGF-ß1 and connective tissue growth factor (CTGF or CCN2), resulting in fibroblast activation or inflammation processes." (PMID 34439556, 2021). "Synergy between CCN2 and TGF-β has been reported in a mouse fibrosis model." (PMID 28267785, 2017).
Myocardial fibrosis (88 papers, 2012 to 2025). "CCN2 is considered an important mediator of myocardial fibrosis elevated in myocardial tissue in animal models as well as in patients with heart failure." (PMID 34854055, 2022). "CCN2 is a pro‐fibrotic cytokine that is involved in the process of myocardial fibrosis." (PMID 37313693, 2023). "In addition, transcript levels of a selected number of genes involved in myocardial fibrosis, namely, Ctgf (Ccn2), Postn, Col1a1, Col5a2, and Timp, quantified by RT-PCR, were also increased in the Pdgfra-Cre:LmnaF/F mouse hearts." (PMID 35891706, 2022). "It has been demonstrated that CTGF, also known as CCN2, may play roles in the hypertension-induced myocardial fibrosis through regulation of TGF-β expression." (PMID 33569393, 2020). "In DCM model rats, CTGF/CCN2 gene silencing improved cardiac function, attenuated myocardial fibrosis, and left ventricular hypertrophy." (PMID 33014530, 2020). "Moreover, a recent study comparing patients that underwent septal myectomy due to cardiac hypertrophy to structurally normal hearts that were harvested following non-cardiac-related deaths showed that CCN2/CTGF was significantly upregulated and appeared to be a key mediator of myocardial fibrosis." (PMID 35629393, 2022).
pancreatic cancer (79 papers, 2004 to 2025). "Abnormal CCN2 expression is associated with the progression of multiple cancers, including breast, prostate and pancreatic cancers." (PMID 39956959, 2025). "CCN2 expression increased in hypoxic pancreatic tumor cells to protect cells from hypoxia-mediated apoptosis." (PMID 40724877, 2025). "FG-3019 is a monoclonal antibody against CCN2 that was tested in locally advanced or metastatic pancreatic cancer in a phase I study." (PMID 26497214, 2016). "Promising pre-clinical studies showing inhibition of metastasis of breast and pancreatic cancer using antibodies to CTGF/CCN2 further validate this concept." (PMID 23977121, 2013). "Curiously, neutralizing anti-CCN2/CTGF antibody attenuated metastasis pancreatic cancer." (PMID 25120383, 2014). "Indeed, CTGF/CCN2 expression and secretion was increased in hypoxic pancreatic tumor cells in vitro, and co-localized with hypoxia in pancreatic tumor xenografts and clinical pancreatic adenocarcinomas." (PMID 26029109, 2015).
diabetic nephropathy (73 papers, 2008 to 2025). "Interestingly, in several independent studies, circulating or urinary levels of CCN2 have been proposed as a risk biomarker of human diabetic nephropathy and other forms of CKD." (PMID 35204752, 2022). "It has anti-fibrotic and anti-proliferative properties, is implicated in tissue repair, and is a negative regulator of CCN2 in a diabetic nephropathy model and mouse scleroderma model." (PMID 37762168, 2023). "CTGF (also known as CCN2) is involved in comprehensive regulatory processes in angiogenesis, chondrogenesis, osteogenesis, inflammation, fibrogenesis, diabetic nephropathy, and tumor development." (PMID 32801999, 2020). "This is consistent with previous observations that an approximately 50 % reduction of CCN2 expression by genetic deletion or siRNA was sufficient to significantly attenuate models of diabetic nephropathy and obstructive nephropathy." (PMID 27766493, 2017). "In diabetic nephropathy, the activation of Wnt signaling in mesangial cells by CCN2 was along with stimulated phosphorylation of LRP6, nuclear localization of β-catenin, and expression of Wnt targets." (PMID 28870205, 2017). "The direct relationship of aldosterone and CCN2 expression in diabetic nephropathy had also been studied." (PMID 26421309, 2015). "A recent study has shown that (Pro)renin receptor (PRR) promoted the progression of diabetic nephropathy through enhanced TGFβ1 CCN2 signaling cascade, which was evidenced by administering PRR blockade in vivo and in vitro." (PMID 26421309, 2015). "In this review, we will summarize some potential renoprotective agents which can wholly or partly inhibit CCN2 for delaying the development and progression of diabetic kidney disease." (PMID 26421309, 2015). "And CCN2 has also become an index to auxiliarily verify the protective effect of some drugs or agents on diabetic nephropathy." (PMID 26421309, 2015). "CCN2 was first identified as a profibrotic mediator which was upregulated both in vitro and in vivo models of diabetic nephropathy." (PMID 23936844, 2013). "The Rho family member Cdc42 was also found uniquely to be activated in cells treated with TGFβ and CCN2; Cdc42 interacting genes were differentially regulated in diabetic nephropathy." (PMID 23902294, 2013). "Preclinical studies have shown that inhibition of endogenous CCN2 by antisense oligonucleotides or gene silencing slows disease progression in experimental diabetic nephropathy, unilateral ureteral obstruction, and nephrectomized transgenic mice overexpressing TGF-β1." (PMID 35204752, 2022). "CCN2/CTGF is an established effector of TGFβ driven responses in diabetic nephropathy." (PMID 23902294, 2013). "Exendin-4 also exerted potential protective role in diabetic nephropathy by prohibiting high glucose-induced human mesangial cells (HMCs) proliferation and decreasing the expression of TGF-β1 and CCN2." (PMID 26421309, 2015). "Connective tissue growth factor (CTGF; CCN2) plays a role in the development of diabetic nephropathy (DN)." (PMID 26171399, 2015). "Some specific and nonspecific CCN2 inhibitors addressed in this review have shown potential renoprotective effects and highlight the future of the treatment of diabetic nephropathy." (PMID 26421309, 2015). "Up to date, a wide variety of agents or drugs have shown their renoprotective properties through different mechanisms in diabetic nephropathy, but not all of the agents have the ability to inhibit the expression of connective tissue growth factor (CCN2)." (PMID 26421309, 2015). "TGFβ and CCN2 attenuate CREB and augment E2F1 transcriptional activation with the likely effect of altering actin cytoskeletal and cell growth/hypertrophic gene activity with implications for cell dysfunction in diabetic kidney disease." (PMID 23902294, 2013).
diabetic nephropathy (continued). "Moreover, administration of simvastatin with the dose of less than cholesterol-lowering (2 mg/kg/d) attenuated the progression of the tubulointerstitial fibrosis by reducing the expression of CCN2 and α-SMA in renal tubulointerstitium of diabetic nephropathy rats." (PMID 26421309, 2015).
melanoma (53 papers, 2007 to 2026). A malignant, usually aggressive tumor composed of atypical, neoplastic melanocytes. "A different scRNA seq analysis of 46 human melanomas found that tumors with high CAF CCN2 expression was associated with worse disease free survival and more neoangiogenesis." (PMID 38525245, 2024). "A recent study using B16F10 melanoma cells deficient in CCN2 (connective tissue growth factor) also highlighted the importance of periostin for melanoma metastasis." (PMID 30621220, 2019). "A different study of >4,000 cells from 46 primary human melanomas and TCGA data showed that high tumor CCN2 expression correlates with worse disease-free survival." (PMID 38525245, 2024). "COL1A2 is also a fibroblast-specific promoter that affects melanoma angiogenesis and metastasis via the influention of the connective tissue growth factor (CCN2)/CAF pathway." (PMID 37762054, 2023). "In human melanoma patients, cellular communication network factor 2 (CCN2) is overexpressed by CAFs and negatively correlated with disease-free outcomes." (PMID 36077754, 2022). "In malignant melanoma and gastric cancer, CCN2 promotes cell invasion and migration." (PMID 29029514, 2017). "The connective tissue growth factor (CTGF or CCN2) is a cysteine-rich matricellular protein highly secreted into the ECM by both malignant melanoma cells and activated fibroblasts within the tumor mass." (PMID 34067929, 2021). "During the formation of VM structures in melanoma, CAF malignantly overexpress the stromal cell protein CCN2 (formerly known as connective tissue growth factor, CTGF); when CAF activation is inhibited, the formation of VM structures is significantly affected." (PMID 33397409, 2021). "Furthermore, WAY-316606 markedly impaired the migratory and invasive capacities of metastatic melanoma cells, accompanied by downregulation of key ECM remodeling and fibrosis-related genes, including VIM, CCN2, FN1, and TGFBI." (PMID 42279305, 2026). "JQ1 was characterized by induction of inhibitory relationship linking regulators of inflammation (IFNG, IL17A, TGFB2), melanoma biological behavior (EGFR, WNT3A, TEADs, MRTFB), cell-cell interaction (CD44, CCN2), YAP pathway (LLGL2, NSUN6) and main transcriptional regulators (FOS, JUN, FOXM1)." (PMID 36397155, 2022). "Their work has shown that CCN2 (formerly known as Connective Tissue Growth Factor or CTGF) expressed by CAFs is essential for tumor vascularization, making it a novel target for treating melanoma." (PMID 35892569, 2022).
cardiac hypertrophy (51 papers, 2011 to 2025). "The PPI analysis identified CCN2/CTGF, which encodes for the protein ‘connective tissue growth factor’, as a central hub node, indicating an important role in the progression of cardiac hypertrophy." (PMID 35629393, 2022). "Likewise, appending the CK domain of CCN2 onto CCN5 caused enhanced myocardial hypertrophy, similar to that elicited by CCN2." (PMID 37245184, 2023). "Similarities of these domains has been illustrated by removing the CK domain from CCN2 causing CCN2 to act similar to CCN5, i.e. to inhibit myocardial hypertrophy following aortic constriction in mice." (PMID 37245184, 2023). "This supports the fact that CCN2/CTGF is an important protein in cardiac hypertrophy development and likely of high relevance for benchmarking hypertrophy progression." (PMID 35629393, 2022). "CCN2/Connective tissue growth factor seems to be involved in development of cardiac hypertrophy and fibrosis, but a possible cardioprotective role in left ventricular (LV) remodelling following myocardial infarction has also been suggested." (PMID 28931920, 2017). "This study supports the potential role of CCN2/CTGF as a biomarker of cardiac hypertrophy." (PMID 35629393, 2022). "The protein-interaction network analysis revealed CCN2 as a central node among the 25 overlapping DEGs, suggesting that this gene might play an important role in the development of cardiac hypertrophy." (PMID 35629393, 2022). "CCN5 exerted an opposing function in CCN2-induced cardiac hypertrophy and fibrosis." (PMID 25901787, 2015). "In the study, CCN2/CTGF and THBS1 were identified as interesting candidate cardiac hypertrophy biomarkers that are expressed in both the ET-1-induced cardiac hypertrophy in vitro model and the hypertrophic cardiac biopsies at both gene and protein levels." (PMID 35629393, 2022). "In this paper, we identified and validated two potential cardiac hypertrophy markers, CCN2/CTGF and THBS1." (PMID 35629393, 2022). "For instance, angiotensin II is a well-known fibrotic factor for cardiac hypertrophy and fibrosis and can directly induce TGFβ and CCN2/CTGF." (PMID 30695033, 2019). "Other studies indicate that conditional CCN2 deletion fails to mitigate cardiac hypertrophy and fibrosis induced by pressure overload." (PMID 39273564, 2024). "CCN2 and CCN5 were found to be upregulated during the development of cardiac hypertrophy." (PMID 25901787, 2015). "However, CCN2 expression accelerates cardiac fibrosis and hypertrophy, whereas CCN5 exerted anti-hypertrophic and -fibrotic effects, indicating that CCN5 antagonizes CCN2 function during the development of cardiac hypertrophy and fibrosis." (PMID 25901787, 2015).
heart failure (47 papers, 2009 to 2025). Inability of the heart to pump blood at an adequate rate to meet tissue metabolic requirements. "CCN2 has been implicated in various cardiovascular conditions, including heart failure, pulmonary hypertension, restenosis, and atherosclerosis, both in experimental models and in clinical settings." (PMID 39273564, 2024). "Experimental studies have shown that blocking CCN2 is beneficial for pulmonary vascular remodeling and heart failure." (PMID 39273564, 2024). "The protein ‘Cellular Communication Network Factor 2’ (CCN2/CTGF) is known to be induced in heart failure and showed upregulation in the hypertrophic samples in both the in vitro and in vivo data." (PMID 35629393, 2022). "The role of circulating CCN2 as a potential prognostic biomarker for adverse remodelling, heart failure development and long-term prognosis in STEMI patients appears to be limited." (PMID 28931920, 2017). "There are several studies indicating the role of CCN2/CTGF protein as a biomarker for cardiovascular diseases and report that plasma levels of CCN2/CTGF protein correlate with the plasma levels of the known hypertrophy marker BNP in patients with heart failure." (PMID 35629393, 2022). "It has also been suggested that CCN2/CTGF protein could be a biomarker for comparing the severeness of heart failure." (PMID 35629393, 2022). "However, increased levels of CCN2 have been described in experimental and human cardiovascular diseases, including heart failure, pulmonary hypertension, restenosis, atherosclerosis and aortic aneurysms, suggesting CCN2 as a potential therapeutic target." (PMID 36499730, 2022). "Increased CCN2, regulated by F2R, contributed to failure of heart." (PMID 32423033, 2020). "Myocardial CCN2/CTGF is induced in heart failure of various etiologies." (PMID 23284892, 2012). "Thus, despite the increased levels of CCN2 observed in experimental and human cardiovascular diseases, including heart failure, pulmonary hypertension, restenosis, atherosclerosis or aortic aneurysms, the preclinical attempts to regulate CCN2 levels have led into mixed results." (PMID 36499730, 2022). "In an animal disease model of hypertrophic cardiomyopathy with a significant enlargement of the left ventricle and severe heart failure, it was shown that both THBS1 and CCN2/CTGF were significantly upregulated in the diseased condition." (PMID 35629393, 2022).